MAGOHB (mago homolog B, exon junction complex subunit)
Description:
Required for pre-mRNA splicing as component of the spliceosome. Plays a redundant role with MAGOH in the exon junction complex and in the nonsense-mediated decay (NMD) pathway.
Synonyms: FLJ10292; MGN2; mago; magoh
Tractability: Small molecule: a structure with a bound ligand is known. PROTAC: ubiquitination databases record sites on it.
Gene: Protein-coding gene on chromosome 12 (10,604,190 to 10,613,609, reverse strand). Ensembl gene ENSG00000111196.
Subcellular location: Nucleus
Pathways (Reactome):
Metabolism of RNA: Nonsense Mediated Decay (NMD) enhanced by the Exon Junction Complex (EJC); Transport of Mature mRNA derived from an Intron-Containing Transcript; mRNA 3'-end processing; mRNA Splicing - Major Pathway
Developmental Biology: Regulation of expression of SLITs and ROBOs
Gene Ontology:
Molecular function: protein binding; RNA binding
Biological process: mRNA splicing, via spliceosome; nuclear-transcribed mRNA catabolic process, nonsense-mediated decay; mRNA export from nucleus; RNA splicing
Cellular component: exon-exon junction complex; exon-exon junction subcomplex mago-y14; nucleus; U2-type catalytic step 1 spliceosome; U2-type precatalytic spliceosome; catalytic step 2 spliceosome; cytosol; nucleoplasm; neuronal cell body; spliceosomal complex
Genetic constraint (gnomAD): Loss-of-function variants: 7 observed, 5.39 expected, observed/expected ratio (o/e) 1.3, 90% interval 0.71 to 1.9. That is too few expected variants to judge how well the gene tolerates losing a copy. Missense variants: 43 observed, 57.49 expected, observed/expected ratio (o/e) 0.75, 90% interval 0.58 to 0.96. Synonymous variants: 19 observed, 20.23 expected, observed/expected ratio (o/e) 0.94, 90% interval 0.65 to 1.38.
Homologues: Orthologues: macaque MAGOHB (99% identical), rat Magohb (99% identical), rabbit MAGOHB (99% identical), mouse Magohb (98% identical), zebrafish magoh (97% identical), Drosophila melanogaster mago (89% identical), tropical clawed frog magoh (82% identical), Caenorhabditis elegans mag-1 (78% identical), dog MAGOH (72% identical), guinea pig MAGOHB (69% identical). Paralogues in human: MAGOH (97% identical).